GJB2 (gap junction protein beta 2)
Diseases named in the same sentence as GJB2 in open-access papers (continued):
Sharing a sentence is not in itself a finding about the gene and the disease.
sensorineural hearing loss (continued). "In excess of 135 mutations in the GJB2 gene encoding Cx26 have been linked to inherited sensorineural hearing loss ranging from moderate to profound severities but none of these Cx26 mutants have been investigated in a cochlear-relevant cell line that has retained some capacity for differentiation." (PMID 32300592, 2020). "Genetic testing is essential to the diagnosis of nonsyndromic bilateral sensorineural hearing loss (BSNHL), where pathogenic variants in GJB2 are the most common cause." (PMID 41367487, 2025). "The GJB2 (connexin 26) and GJB6 (connexin 30) genes, both at the DFNB1 locus, are most commonly associated with bilateral sensorineural hearing loss, accounting for up to 31% of genetic cases confirmed in a recent study." (PMID 36529647, 2022). "Nearly half of all inherited sensorineural hearing loss is attributed to mutations in one of four members of the 21 connexin gene family, although GJB2 gene (encoding Cx26) mutations linked to hereditary deafness are by far the most common." (PMID 32300592, 2020). "Among the main genetic defects, mutations within connexin 26 (GJB2) and connexin 30 (GJB6) are usually associated with severe to profound sensorineural deafness." (PMID 26323392, 2015). "This study aims to investigate the mutation spectrum of GJB2, mitochondrial 12S rRNA, and SLC26A4 genes of Han Chinese, Hui people, and Uyghur ethnicities in sensorineural hearing loss (SNHL) patients in northwest of China." (PMID 24804242, 2014). "GJB2 is most known for its linkage in children with non-syndromic genetic sensorineural hearing loss and has not been identified previously as having an association with ASD22." (PMID 38287090, 2024). "Connexin 26 or GJB2 (Gap Junction Beta-2 protein) was the first gene identified as responsible for nonsyndromic sensorineural hearing loss." (PMID 36529647, 2022). "To evaluate the added diagnostic value of this microarray for our ethnically diverse patient population, we tested 144 individuals with congenital sensorineural hearing loss who were negative for biallelic GJB2 or GJB6 mutations." (PMID 20668687, 2010). "However, our study has several limitations that must be addressed before clinical application: 1) In terms of model selection, it should be noted that the present study focused on the clinically critical population of very severe sensorineural deafness due to defects in the GJB2 gene." (PMID 40387257, 2025). "This study aims to investigate the mutation spectrum of GJB2, mitochondrial 12S rRNA, and SLC26A4 genes of Han Chinese, Hui people, and Uyghur ethnicities in sensorineural hearing loss (SNHL) patients." (PMID 24804242, 2014).
autosomal recessive deafness (41 papers, 2008 to 2025). "The carrier frequency of pathogenic variants in the GJB2 gene, associated with autosomal recessive deafness 1A, observed in our cohort aligns with previously published data on the Russian population." (PMID 41595422, 2025). "The GJB2 (autosomal recessive deafness 1A) and SERPINA1 (alpha-1-antitrypsin deficiency) genes harbored the second highest carrier frequency of P/LP variants in the study cohort (5.5%)." (PMID 41595422, 2025). "Among 1048 pairs, we found 56 pairs (5.34%) and 9 females (0.57%) at risk for autosomal or X-linked recessive disorders, with GJB2 autosomal recessive deafness 1A (DFNB1A) being the most common." (PMID 38297315, 2024). "Despite the wide genetic heterogeneity of Nonsyndromic autosomal recessive hearing loss, a few mutations in the GJB2 and GJB6 genes (encoding connexin-26 and 30, respectively) account for nearly 50% of the cases in the Mediterranean population." (PMID 34997062, 2022). "The c.35delG (deletion of one guanine in a sequence of six Gs at nucleotides 30–35) is common recessive GJB2 mutation associated with nonsyndromic autosomal recessive hearing loss (DFNB1)." (PMID 33466560, 2021). "Although variations in GJB2 gene almost exclusively cause prelingual autosomal recessive hearing loss, this disorder is very heterogeneous." (PMID 30837189, 2020). "Previous studies have identified GJB2 as in important contributor to hereditary NSHL, and mutations in GJB2 can be detected in nearly 50% of patients with autosomal recessive hearing loss." (PMID 29634755, 2018). "Despite significant heterogeneity of genetic deafness, GJB2 (encoding Gap junction beta-2 protein, also known as connexin 26) causes more than 50% of autosomal recessive nonsyndromic deafness in many populations." (PMID 23637863, 2013). "Worldwide, the most common cause of nonsyndromic autosomal recessive hearing loss is a mutation in connexin 26, a gap-junction protein encoded by the GJB2 gene." (PMID 24341454, 2013). "Worldwide, the most common causes of nonsyndromic autosomal recessive hearing loss are mutations in connexin 26, a gap-junction protein encoded by the GJB2 gene." (PMID 22389666, 2012). "The most common causes of nonsyndromic autosomal recessive hearing loss are mutations in connexin 26, a gap-junction protein encoded by the GJB2 gene." (PMID 21122151, 2010). "For many populations, the most common cause for non-syndromic autosomal recessive hearing loss is mutated Connexin 26, a gap junction protein encoded by the GJB2 gene (MIM 121011)." (PMID 19366456, 2009). "Mutations in the GJB2 gene (13q12.11, OMIM 121011) encoding transmembrane protein connexin 26 result in the nonsyndromic autosomal recessive deafness 1A (DFNB1A, OMIM 220290), which is one of the most common forms of HL in many populations, at least of Caucasian descent." (PMID 34943614, 2021). "The carrier frequencies of top 10 conditions were consistent with the previous reports, the most common disorders screened was GJB2-autosomal recessive deafness 1A (DFNB1A)." (PMID 38297315, 2024). "Pathogenic variants within the DFNB1 locus (13q11-12), which contains the genes GJB2 and GJB6, are estimated to explain near 50% of all cases of autosomal recessive hearing loss in many different countries and regions." (PMID 39498320, 2024). "Autosomal recessive deafness 1A (DFNB1A), caused by mutations in the GJB2 gene (MIM 121011, 13q12.11) encoding the protein connexin 26 (Cx26), is the most prevalent in many populations." (PMID 35205123, 2022). "The aim of this study is to compare the performance of the in silico pathogenicity prediction tools by testing the missense variants in GJB2 (Cx26), GJB6 (Cx30), and GJB3 (Cx31) genes associated with the autosomal recessive deafness 1A." (PMID 31015822, 2019).
autosomal recessive deafness (continued). "Mutations in the GJB2 gene (gap junction protein, beta-2, 13q12.11, MIM 121011) encoding transmembrane protein connexin 26 (Cx26) lead to nonsyndromic autosomal recessive deafness 1A (DFNB1A, MIM 220290) which is the most common form of hereditary hearing loss in many populations." (PMID 32708339, 2020). "The most common form of hereditary nonsyndromic hearing loss is autosomal recessive deafness 1A (DFNB1A, MIM#220290) caused by pathogenic variants in the GJB2, GJB6, and GJB3 genes encoding connexin 26 (Cx26), connexin 30 (Cx30), and connexin 31 (Cx31) proteins, respectively." (PMID 31015822, 2019). "We screened 160 unrelated Japanese with severe to profound recessive nonsyndromic hearing loss (ARNSHL) without GJB2 or SLC26A4 mutations, and 192 controls with normal hearing." (PMID 24053799, 2013).
melanoma (29 papers, 2005 to 2026). A malignant, usually aggressive tumor composed of atypical, neoplastic melanocytes. "Metastatic melanomas showed the loss of GJA1 (Cx43) protein, the increase in cytoplasmic GJB2 (Cx26), and the upregulation of both GJC3 (Cx30.2) and GJB1 (Cx32) through melanoma progression, compared to melanocytes." (PMID 40227837, 2025). "In three melanoma cell lines, we also showed the loss of GJA1/Cx43 and the differential expression of GJB1/Cx32, GJB2/Cx26, GJA3/Cx46 and GJC3/Cx30.2." (PMID 30717194, 2019). "Using this pipeline, we identified CLDN10 and GJB2 as potential tumor suppressors in melanoma." (PMID 41828699, 2026). "In silico data revealed downregulation of GJA1/Cx43 and GJB2/Cx26 mRNA, in addition to upregulated GJB1/Cx32, during melanoma progression." (PMID 30717194, 2019).
keratitis (27 papers, 2011 to 2026). A corneal disease that is characterized by inflammation of the cornea. "We found one example of pLoF variant modifying disease penetrance of a pathogenic variant in GJB2 p.Gly45Glu (13-20189448-C-T) that is reported to cause a severe form of keratitis-ichthyosis-deafness syndrome but found in 35 individuals in gnomAD v4." (PMID 41173899, 2025). "One example was a pathogenic variant in GJB2 p.Gly45Glu (13-20189448-C-T) that is reported to cause a severe form of keratitis-ichthyosis-deafness syndrome but found in 35 individuals in gnomAD v4." (PMID 38915639, 2024). "GJB2 was included in this panel because dominant negative variants are associated with keratitis-ichthyosis-deafness syndrome." (PMID 34697415, 2022). "Germline variants in GJB6 and GJB2 (connexin 26), which are similarly enhanced in this subpopulation, cause keratitis-ichthyosis-deafness syndrome, typified by transient inflammatory erythrokeratoderma." (PMID 30355494, 2018). "Mutations in GJB2, GJB6, and GJA1 result in keratitis, corneal opacity, skin disorders, and hearing loss." (PMID 34381080, 2021).
autosomal recessive hearing loss (26 papers, 2009 to 2026). "The GJB2 gene encodes connexin 26, a gap junction protein associated with autosomal recessive and autosomal dominant non-syndromic deafness, and autosomal dominant hearing loss syndromes combined with skin disorders." (PMID 41546701, 2026). "The GJB2 gene, encoding connexin 26, is a major contributor to nonsyndromic sensorineural hearing loss (NSHL) due to its role in cellular communication critical for auditory function." (PMID 40943139, 2025). "In this study, via traditional PCR and Sanger sequencing, a novel GJB2 heterozygous mutation was identified in a Chinese family with autosomal dominant non-syndromic hearing loss (ADNSHL)." (PMID 28102197, 2017). "Mutations in GJB2 and mitochondrial DNA (mtDNA) 12S rRNA are the most common molecular etiology for nonsyndromic sensorineural hearing loss (NSHL)." (PMID 23826813, 2013). "The GJB2 (Cx26) gene (13q12.11, MIM 121011) pathogenic variants associated with autosomal recessive deafness type 1A (DFNB1A, OMIM #220290) are the main cause of hereditary non-syndromic hearing impairment (HI)." (PMID 37239361, 2023). "The mutation spectrum of the GJB2 gene in Chinese patients with nonsyndromic hearing impairment (NSHI) has not been analyzed." (PMID 19366456, 2009).
ichthyosis (24 papers, 2014 to 2025). Disorders of cornification that are characterized by visible scaling and/or hyperkeratosis of most or all of the skin. "This visual summary underscores the potential for broader, under-recognized manifestations of GJB2 mutations and supports the need for a more expansive diagnostic framework when evaluating patients with suspected syndromic ichthyosis." (PMID 41305774, 2025). "In children with ichthyosis resulting from mutations in the GJB2 gene, hearing loss is predominantly linked to the disruption of gap junctions and their pivotal role in cellular communication within the inner ear." (PMID 40004458, 2025). "The study provides valuable insights into the genetic, clinical, and audiological characteristics of patients with GJB2 mutations and ichthyosis." (PMID 40004458, 2025). "It is well established that patients with GJB2 mutations, who also present with ichthyosis and hearing loss, may experience significant benefits from cochlear implant in terms of auditory perception, speech development, language acquisition, and communication skills." (PMID 40004458, 2025). "The classic form of VS is caused by mutations in the GJB2 gene, while a variant form of VS, characterized by ichthyosis and VS without hearing loss, is caused by a single-base pair insertion mutation in the LOR gene, encoding for loricrin." (PMID 38827992, 2024). "These two non-classical variants in GJB2 have already been described as causative of non-syndromic hearing loss, ichthyosis and in some cases keratoderma on the palms and soles which are consistent with the observed phenotype." (PMID 37811145, 2023). "GJB2 and GJB6 have also been associated with ichthyoses, keratoderma, and ectodermal dysplasias." (PMID 37239394, 2023).
nonsyndromic hearing loss (24 papers, 2011 to 2025). "Previous studies have identified 123 genes with variants associated with NSHL, among which GJB2 was a contributor to 50% of autosomal recessive Non-Syndromic Hearing Loss (NSHL) cases." (PMID 39754783, 2025). "The carrier frequency of PV and PLV in GJB2, one of the most common genes causing nonsyndromic deafness is 0.6% (9/1642)." (PMID 38167091, 2024). "Although hundreds of genes have been reported to be associated with nonsyndromic hearing loss, GJB2, SLC26A4, and mtDNA12SrRNA are the major contributors." (PMID 27247933, 2016). "As for genetic factors of nonsyndromic deafness in China, the average value of variant in GJB2 seems to be the most common (23.37%), followed by SLC26A4 (14.74%), mtDNA 12SrRNA A1555G ( 2.44%), GJB3 (1.97%) and GJB6 (1.33%) genes." (PMID 23554706, 2011). "Most GJB2 mutations cause recessive non-syndromic deafness (DFNB1A, OMIM: 220290)." (PMID 36187349, 2022). "Screening gene mutation of GJB2 could contribute to gene diagnosis and genetic counseling in families with Non-Syndromic Hearing Loss (NSHL)." (PMID 36193416, 2022). "Consistent with its role as the leading common genetic cause of non-syndromic hearing loss (NSHL) in China, GJB2 variants (autosomal recessive inheritance, population carrier rate 2%–3%) were the most frequently identified in our study." (PMID 41181184, 2025). "Nonsyndromic hearing loss (NSHL) is of great clinical importance, and mutations in the GJB2 gene and the encoded human CONNEXIN 26 (CX26) protein play important roles in the genetic pathogenesis." (PMID 32455934, 2020). "Although hundreds of genes have been reported to be associated with nonsyndromic hearing loss (NSHL), GJB2, GJB6, SLC26A4, and mitochondrial (mt) MT-RNR1 and MTTS are the major contributors." (PMID 28273078, 2017).
Palmoplantar keratoderma (22 papers, 2009 to 2026). Abnormal thickening of the skin of the palms of the hands and the soles of the feet. "Sequence analysis of the GJB2 gene indicated that 51 patients carried two confirmed pathogenic mutations, and 1 patient had an R75W mutation, which has been reported to cause autosomal dominant syndromic deafness with palmoplantar keratoderma." (PMID 19744334, 2009). "Furthermore, mutations in other connexins, such as Cx26 (encoded by GJB2), can cause some overlapping features of HED including nail dystrophy, hair loss, and palmoplantar keratoderma." (PMID 32843087, 2020). "For example, it is not uncommon for patients with EKVP to also have palmoplantar keratoderma, which is predominantly attributable to mutations in GJB2." (PMID 31817921, 2019).
colorectal cancer (16 papers, 2010 to 2024). A primary or metastatic malignant neoplasm that affects the colon or rectum. "We analyzed spatial resolved transcriptome data using 10xVisium in colorectal cancer, to visualize the spatial positioning of CAFs expressing GJB2 and vascular endothelial cells." (PMID 37648762, 2023). "In a study of colorectal cancer, high GJB2 expression was related to venous invasion, lung metastasis, and poor disease-free survival." (PMID 35936685, 2022). "Moreover, we analyzed GJB2 mRNA expression in different cancers and found that GJB2 was also enriched in cancer cells of intrahepatic cholangiocarcinoma and colorectal cancer." (PMID 39162005, 2024). "(E) Images of co-cultures from eight colorectal cancer (CRC) lines, ranked by increasing GJB2 message, acquired from confluent and low-confluency regions." (PMID 36107487, 2022).
psoriasis (14 papers, 2017 to 2025). An autoimmune condition characterized by red, well-delineated plaques with silvery scales that are usually on the extensor surfaces and scalp. "Previous studies have found that the polymorphism of GJB2 gene and the high expression of Cx26 are strongly correlated with the pathogenesis of psoriasis." (PMID 36193416, 2022). "The combined transcriptomic and DNA methylation data resulted in 33 differentially expressed methylated genes, of which GJB2 was the final identified hub gene for psoriasis, with robust diagnostic power." (PMID 36193416, 2022). "Rs72474224 and Rs3751385 in GJB2 were preferentially associated with psoriasis susceptibility of the Chinese Han population." (PMID 36193416, 2022). "GJB2, encoding CX26 was the 98th most up-regulated gene detected and its over expression is used as a marker of genetic predisposition in psoriasis." (PMID 33466954, 2021). "GJB2, which encodes CX26, is the 98th most upregulated gene detected, and its overexpression is used as a marker of genetic predisposition in psoriasis." (PMID 34639182, 2021). "Studies have also shown that both the ZNF816A and GJB2 loci are significantly associated with psoriasis in the German population, while ERAP1 and ZNF816A are associated with type 1 (early-onset) psoriasis in the Chinese Han population." (PMID 29292715, 2017). "Finally, a variant in the GJB2 gene, encoding a connexin, was found as a psoriasis risk locus by GWAS." (PMID 37628670, 2023). "This evidence suggested that GJB2 was a potential diagnostic marker for psoriasis." (PMID 36193416, 2022). "To further investigate the expression of GJB2 in psoriasis, we performed IHC staining and real-time qPCR using 8 psoriasis lesions and 11 healthy skin tissues." (PMID 36193416, 2022). "IHC and RT-qPCR showed that GJB2 was significantly higher in psoriasis samples than those in healthy controls." (PMID 36193416, 2022). "Inspired by this, we believed that GJB2 was most likely a hopeful therapeutic target to be developed for psoriasis." (PMID 36193416, 2022). "Then, GJB2 was the only overlapped gene among the three machine learning methods, which was identified as the hub gene for psoriasis." (PMID 36193416, 2022). "Our single-gene GSEA also suggested that GJB2 may be involved in the development and progression of psoriasis by regulating immune microenvironment of skin and destroying the skin barrier, which is consistent with the previous finding." (PMID 36193416, 2022). "Moreover, we assessed the DNA methylation levels of GJB2 between the normal and psoriasis groups in GSE73894, and the results showed that the DNA methylation levels of GJB2 were significantly lower in the psoriasis group." (PMID 36193416, 2022). "The abnormal expression of GJB2 might play a critical role in psoriasis development and progression." (PMID 36193416, 2022). "Finally, the expression and methylation level of GJB2 in psoriasis were verified by the external dataset and qRCR." (PMID 36193416, 2022). "Enhanced Cx26 and Cx30 protein expression is highly evident in psoriatic plaques and a transcriptome analysis revealed GJB2, to be among the top 100 genes upregulated in psoriasis, with its expression levels increased up to 18-fold in psoriatic lesions compared to normal tissue." (PMID 29751558, 2018). "In conclusion, this study indicated that GJB2 could be a key target for the diagnosis and treatment of psoriasis through combined multiomics, and single-gene GSEA revealed that GJB2 might induce psoriasis by regulating body immunity and destroying skin barrier." (PMID 36193416, 2022). "In addition, reversing the hypomethylation of GJB2 might be a new strategy for the treatment of psoriasis in the future." (PMID 36193416, 2022). "The downregulated genes detected at day 14 in these populations included inflammatory molecules (e.g., IL36G, S100A7/A8/A9) and structural proteins (GJB2, KRT16/17), known to be over-expressed in the upper layers of the psoriasis epidermis." (PMID 38291032, 2024).